CCL3 (C-C motif chemokine ligand 3)
Diseases named in the same sentence as CCL3 in open-access papers (continued):
Sharing a sentence is not in itself a finding about the gene and the disease.
cholangitis (1 paper, 2018). An acute or chronic inflammatory process affecting the biliary tract. "Therapeutic blockade of IL-15 in obese mice with cholangitis resulted in attenuated histological damage, lower numbers of infiltrating neutrophils and CD8+ T cells and reduced levels of proinflammatory cytokines and chemokines including IL-13, IL-17, C-GSF, CCL2, CCL3 and CXCL10." (PMID 29449577, 2018).
chordoma (1 paper, 2010). Chordomas are rare malignant tumors arising from embryonic remnants of the notochord in axial skeleton. "Our analyses revealed that CCL3, CCL4, and GB60 are not chordoma cell lines, and that CM319 is a cancer cell line possibly derived from chordoma, but lacking expression of key chordoma biomarkers." (PMID 21253487, 2010).
chronic pancreatitis (1 paper, 2022). A chronic inflammatory process causing damage and fibrosis of the pancreatic parenchyma. "Compared with DMBA-treated WT mice, DMBA-treated TG mice showed lower mRNA levels of CD68, a marker of macrophages; Cxcl9, a four-chemokine signature in primary and metastatic PC; and Ccl3, which plays an important role during chronic pancreatitis." (PMID 35504863, 2022).
Cm (1 paper, 2025). "Collectively, these results indicate that NK cell depletion reduces CCR5, CCL3, and CCL5 levels, consequently impairing DC recruitment and migration during Cm infection." (PMID 40332391, 2025).
cocaine addiction (1 paper, 2023). "One chemokine receptor system involved in the pathophysiology of cocaine addiction is CCR5, whose ligands are CCL3 and CCL5." (PMID 36830990, 2023).
demyelination (1 paper, 2020). "Immunization with MOG peptide, i.e., induction of EAE during CPZ-induced demyelination resulted in microglia activation in contrast to classic EAE, and also potentiated gene expression of CXCL10, CCL2, and CCL3 in the corpus callosum beside additional brain areas." (PMID 32582192, 2020).
diabetic eye disease (1 paper, 2024). A group of disorders affecting the eye in patients with diabetes mellitus. "However, concentrations of chemokines (CCL3, CCL9 and CXCL1) retained no significance alone and concentrations of chemokines (CCL5 and CXCL4) were lower in the diabetic eye disease patients than in the controls." (PMID 38790059, 2024).
diabetic foot ulcers (1 paper, 2022). "We posit that CCL3 may have therapeutic potential for the treatment of diabetic foot ulcers if it is applied topically after the surgical debridement process which is intended to reset chronic ulcers into acute fresh wounds." (PMID 35112667, 2022). "However, given that diabetic foot ulcers are already suffering from neutrophilia and heightened inflammation, the therapeutic value of CCL3 treatment may seem questionable." (PMID 35112667, 2022).
dysplasia (1 paper, 2024). A usually neoplastic transformation of the cell, associated with altered architectural tissue patterns. "Baseline probability associated with the presence of dysplasia and its grade was affected solely by CCL3, specifically, by ratio of its expression between polyp and non-transformed adjacent mucosa." (PMID 38338661, 2024).
eosinophilic esophagitis (1 paper, 2016). Eosinophilic esophagitis (EoE) is a chronic, allergic disease of the esophagus characterized clinically by symptoms of esophageal dysfunction (including vomiting, dysphagia, feeding disorders, food impaction and abdominal pain) which persist after treatment with proton pump inhibitors (PPIs). "Besides, IL-13 has been implicated in inflammation and remodeling by inducing chemokines (CCL-3, CCL-4, CCL-5 and CXCL-1), and IL-13 is a direct inducer of both CCL11 and CCL24 in eosinophilic esophagitis." (PMID 27533463, 2016).
ependymoma (1 paper, 2021). A WHO grade II, slow growing tumor of children and young adults, usually located intraventricularly. "We noticed that microglia from the normal brain showed high expression of CCL2 and CCL3, resembling tissue-resident CCL2+ TAMs in ependymoma." (PMID 34824203, 2021).
epithelial dysplasia (1 paper, 2017). "Next, we analysed CCL3 expression in human samples of healthy oral mucosa, potentially malignant disorder oral leukoplakia (OLK) with different grades of epithelial dysplasia, and primary OSCC samples." (PMID 28881626, 2017). "OLK with different grades of epithelial dysplasia exhibited similar CCL3 expression, which may suggest that this chemokine does not influence the early stages of oral carcinogenesis." (PMID 28881626, 2017).
esophagitis (1 paper, 2025). An acute or chronic inflammatory disease affecting the esophageal wall. "Reduced severity of esophagitis was associated with downregulation of EGF, IL-16, CCL3, CCL7, and prolactin, suggesting decreased inflammation." (PMID 39808500, 2025).
Ewing sarcoma (1 paper, 2023). A small round cell tumor that lacks morphologic, immunohistochemical, and electron microscopic evidence of neuroectodermal differentiation. "The CCL3+ Mφ subset was composed of cells derived from patient ES-025 and ES-026, indicating that these patients had an enrichment of the proinflammatory macrophage population, as in most Ewing sarcoma patient samples they were of low abundance." (PMID 37823774, 2023).
Farber disease (1 paper, 2023). "Additionally, increased plasma levels of IL6, IL10, IL12, CCL2, CCL3, CXCL1, and VEGF and substantial central nervous system defects have been observed in patients with Farber disease." (PMID 37189685, 2023).
gastric ulcer (1 paper, 2021). An ulcerated lesion in the mucosal surface of the stomach. "Meanwhile, chrysin activated peroxisome proliferator activated receptor-γ (PPAR-γ) and lowered the expression of pro-inflammatory marker genes, including TNF-α, IL-6, and CCL3, to fight indomethacin-induced gastric ulcer." (PMID 35008842, 2021).
glomerulonephritis (1 paper, 2016). A renal disorder characterized by damage in the glomeruli. "MIP1-α/CCL3 belongs to the CC chemokine family that act on recruitment of several leukocytes, and up-regulation of this chemokine was suggested to be responsible for the recruitment of leukocytes in glomeruli in patients with glomerulonephritis." (PMID 27219334, 2016).
glomerulopathy (1 paper, 2015). "For instance, as recently reviewed, the chemokines CCL2, CCL3, and CCL4 correlate with the severity of S. mansoni, where CCL3 is related to the recruitment of eosinophils and induction of granulomatous pathology, while CCL2 is associated with glomerulopathy." (PMID 26082781, 2015).
hairy cell leukemia (1 paper, 2015). Hairy cell leukemia (HCL) is a rare type of leukemia in which abnormal B-lymphocytes are present in the bone marrow, spleen and peripheral blood. "Similar inhibitory effects on proliferation and survival, CCL3/CCL4 secretion, and CXCL12 signaling occur in hairy cell leukemia (HCL) treated with ibrutinib." (PMID 26022368, 2015).
Heat Stroke (1 paper, 2023). A condition caused by the failure of body to dissipate heat in an excessively hot environment or during PHYSICAL EXERTION in a hot environment. "In primary cultured astrocytes, scRNA-seq and qPCR showed upregulation of C6, CCL3, and CCR1 after heat stress but downregulation in heat stroke rats, while the transcriptional levels of CCL3 and CCR1 were downregulated in heat stroke rats." (PMID 37078089, 2023).
hemorrhagic stroke (1 paper, 2022). A stroke caused by a bleed on the brain. "The roles of CCL3 in hemorrhagic stroke have not been studied as extensively as CCL2." (PMID 36704330, 2022). "No clinical studies were searched about CCL3 in patients with hemorrhagic strokes." (PMID 36704330, 2022).
hepatic granuloma (1 paper, 2020). A granuloma located in the liver. "We found that this sensor influences the formation of hepatic granuloma, altering local chemokine (CCL2, CCL3, and CXCL1) and cytokine (IL-5, IL-10, and IL-13) production, macrophage and neutrophil recruitment into the liver, and also is important for promoting collagen deposition." (PMID 32431709, 2020).
hepatitis B (1 paper, 2016). "CCL5 and CCL3 are well characterized as inflammation-associated chemokines, and their main receptor, CCR5, is also essential in hepatitis B progression." (PMID 27994596, 2016). "Because CCR5, a major chemokine receptor for CCL3 and CCL5, is known to be critical in hepatitis B, Ku70/80 sensing of HBV DNA likely plays a critical role in immune cell recruitment in response to HBV infection." (PMID 27994596, 2016).
histiocytic sarcoma (1 paper, 2026). An aggressive malignant neoplasm with a poor response to therapy, usually presenting as stage III/IV disease. "C-C motif chemokine ligand 3 (CCL3) was strongly correlated with tumor necrosis factor-alpha (TNF-α) secretion exclusively in histiocytic sarcoma cells, and recombinant CCL3 induced dose-dependent TNF-α secretion from macrophages." (PMID 42030266, 2026).
hypercoagulability (1 paper, 2019). "This study supports an inverse association between CCL3 levels and hypercoagulability, which is in line with our finding of an association of lower systemic CCL3 levels with higher risk of VTE occurrence in patients with glioma." (PMID 31847343, 2019).
Hyperglycemia (1 paper, 2025). An increased concentration of glucose in the blood. "Hyperglycemia leads to an enhanced expression of chemokines in kidney tissue, such as CCL2, CCL3, CCL4, CCL5, and CXCL12, involving in immune cell recruitment and modulating the inflammation." (PMID 40046045, 2025).
hyperlipidemia (1 paper, 2012). "Thus, it is possible that CCL3 and hyperlipidemia are mechanistically linked." (PMID 22359597, 2012). "Similarly, CCL3 has been shown to be elevated in the plasma and metabolic tissues (liver and adipose tissue) of patients with hyperlipidemia and metabolic disease." (PMID 22359597, 2012). "Taken together these data provide evidence that CCL3 may be an important link in metabolic processes associated with hyperlipidemia; however, the mechanism by which this occurs is not clear." (PMID 22359597, 2012).
hypoglycaemia (1 paper, 2024). "In addition, CXCL9, CCL23, CCL3 and CLL4 increased in response to hypoglycaemia, which can recruit immune cells, thus potentially contributing to the persistently elevated levels of circulating white blood cells." (PMID 38331900, 2024).
hypoxic-ischemic encephalopathy (1 paper, 2024). "It is worth mentioning that primary rat microglia, when subjected to oxygen glucose deprivation as an in vitro model of neonatal hypoxic-ischemic encephalopathy, exhibit heightened production of MIP-1α (also known as Ccl3)." (PMID 38347225, 2024).
idiopathic inflammatory myopathies (1 paper, 2024). "Bub1b encodes a protein associated with mitotic checkpoint control, and Ccl3 is a critical chemokine for idiopathic inflammatory myopathies, with high expression in injured skeletal muscle and responsible for recruiting Treg cells to these sites." (PMID 38339055, 2024).
ileitis (1 paper, 2024). "Other differences in circulating cytokines were also noted including increases in IL-5, CCL3 and CCL4 that were not seen in SHIP-1−/− without ileitis." (PMID 39432107, 2024).
immune deficiency (1 paper, 2016). "CCL3 is important for T cell and monocyte trafficking and a key function of CCL21 is in T cell and DC homing to lymph nodes, which explains in part the role of deficient chemokines in the immune deficiency state of CKD stage 5." (PMID 27795695, 2016).
inflammatory bone diseases (1 paper, 2025). "Additionally, the reduced expression of immune cell recruitment markers, including CCL3 and CCL5, points to an anti-inflammatory effect, potentially mitigating bone resorption in inflammatory bone diseases." (PMID 40711169, 2025).
invasive candidiasis (1 paper, 2012). "In separate experiments, induction of Ccr1 and its ligands Ccl3, Ccl5, Ccl6, Ccl7, Ccl8 and Ccl9 by invasive candidiasis was examined in greater detail in mice injected with 1.25×105 CFU of C. albicans, which causes ∼80% mortality by day 14 post-infection." (PMID 22916017, 2012).
invasive carcinoma (1 paper, 2017). A carcinoma that is not confined to the epithelium, and has spread to the surrounding stroma. "Noteworthy, while the WT mice exhibited pronounced cytological atypia and dysplasia (100% of lesions were graded as invasive carcinoma – score 5), the CCL3-/- mice treated with a higher dose of 4NQO did not present any score of “invasive carcinoma” (data not shown)." (PMID 28881626, 2017).
Kaposi's sarcoma (1 paper, 2017). A malignant neoplasm characterized by a vascular proliferation which usually contains blunt endothelial cells. "In addition, in Kaposi sarcomas D6/ACKR2 delays tumor progression through inhibition of inflammatory chemokines CCL-2, CCL-5 and CCL-3 and reduces macrophage infiltration and angiogenesis." (PMID 28740576, 2017).
keloid (1 paper, 2023). An irregularly shaped, elevated mark on the skin caused by deposits of excessive amounts of collagen during wound healing. "In this study, CCL2 and CCL3 expression was significantly elevated in the perigraft and intragraft areas, contributing to keloid-lesion integrity and augmenting fibrosis." (PMID 37524866, 2023). "The CCL3 level is increased in the plasma of keloid patients." (PMID 37524866, 2023). "Additionally, CCL3, CCL4, G-CSF, and GM-CSF levels were significantly elevated in the plasma of keloid patients compared to healthy controls, implicating inflammatory cytokines in the formation of keloid lesions." (PMID 37524866, 2023).
keratitis (1 paper, 2018). A corneal disease that is characterized by inflammation of the cornea. "CCL2 and CCL3 are critical to the recruitment of neutrophils in the context of keratitis." (PMID 29661181, 2018).
kidney tumor (1 paper, 2023). "In a kidney tumor, we identify 924 DCI genes involved in cell-type-specific functions such as PDE10A in tumor cells and CCL3 in lymphocytes." (PMID 37433798, 2023).
Klebsiella pneumonia (1 paper, 2017). An pneumonia caused by infection with Klebsiella. "Furthermore, CCL3 induces macrophage activation and the killing of Escherichia coli, Trypanosoma cruzi, or Klebsiella pneumonia." (PMID 28265273, 2017).
liver failure (1 paper, 2021). A liver disease characterized by the liver losing or has lost all of its function. "Several elevations signified an emergence of liver failure in the urine level of CCL3, KLRD1, MUC-16, KIRLD1, TWEAK, VEGF r2." (PMID 34608231, 2021).
long QT syndromes (1 paper, 2020). "Therefore, strategies that reduce CCL3 expression in the heart tissue may improve the prognosis of chronic heart diseases associated with TNF-enriched inflammation, as CCC and long QT syndromes." (PMID 32194558, 2020).
macular degeneration (1 paper, 2021). Loss of vision in the central portion of the retina (macula), secondary to retinal degeneration. "Median CCL3 and CCL5 concentrations were significantly decreased in the macular degeneration group compared with controls (p < 0.001) as well as when a cutoff value comparison was used." (PMID 34869411, 2021).
medulloblastoma (1 paper, 2025). A malignant, invasive embryonal neoplasm arising from the cerebellum. "They found significantly elevated levels of CCL3 in the cerebrospinal fluid (CSF) of children with metastatic medulloblastoma compared to non-metastatic cases." (PMID 41153795, 2025).
melancholia (1 paper, 2024). A subtype of depression characterized by the inability to find pleasure in positive things combined with physical agitation, insomnia, or decreased appetite. "We found that 53.2% of the variance in melancholia was explained by the regression on IL-16 and SCGF (both positively) and CCL3 (inversely)." (PMID 38538641, 2024).
metastatic melanoma (1 paper, 2021). A melanoma that has spread from its primary site to another anatomic site. "A study looking at metastatic melanoma biopsies showed that up-regulation of several chemokines, including CCL2, CCL3, CCL4, CCL5, CXCL9, and CXCL10 could be correlated with the presence of T cells in the tumor." (PMID 34207884, 2021).
mycobacterial infection (1 paper, 2022). "Among the molecules, chemokines (CCL3, CCL4, CCL5) and cytokines (IL6, IL1B) are known to induce M1 macrophage polarization in response to mycobacterial infection." (PMID 35821058, 2022).
myelodysplastic syndrome (1 paper, 2018). A clonal hematopoietic disorder characterized by dysplasia and ineffective hematopoiesis in one or more of the hematopoietic cell lines. "CCL3 has also been implicated as a factor leading to microenvironmental dysfunction in a variety of malignancies including myelodysplastic syndrome (MDS), metastatic disease of renal cell carcinoma, and B-Cell lymphomas." (PMID 30279500, 2018).
neurofibroma (1 paper, 2017). An intraneural or extraneural neoplasm arising from nerve tissues and neural sheaths. "In neurofibroma, Tlr2 is slightly down-regulated (0.78x) in 7-month-old neurofibroma macrophages, and Ccl2 and Ccl3, which can increase Tlr2 expression, are not significantly up-regulated." (PMID 28256556, 2017).
neutrophil leukemia (1 paper, 2023). "RNA-seq analysis of the Treg subpopulation from the murine CLL model revealed its unique phenotype characterized by upregulation of multiple factors, including Il10, Ifnγ, and the chemokines Ccl3/4/5 Cxcl13, which likely contribute to the neutrophil leukemia-supporting phenotype." (PMID 37817276, 2023).
obliterative bronchiolitis (1 paper, 2016). "The expression of Ccl3, Ccl4, and Il6 were all down-regulated in macrophages exposed to NR58-3.14.3 and are consistent with the down-regulation of Il6 observed in experimental obliterative bronchiolitis following administration of NR58-3.14.3." (PMID 26911327, 2016).
ocular infection (1 paper, 2018). "Both CCL2 and CCL3 were upregulated in the context of TLR4-mediated inflammation after B. cereus ocular infection, and their blockade might reduce neutrophil infiltration into the vitreous and decrease damage to the retina." (PMID 29661181, 2018).
pancreatic adenocarcinoma (1 paper, 2023). "Notably, CCR5 ligands Ccl3 and Ccl4 are upregulated when DKK1 is expressed and have previously been shown to be strong mediators of Treg infiltration in pancreatic adenocarcinoma." (PMID 35924447, 2023).
pituitary tumor (1 paper, 2023). A benign or malignant neoplasm affecting the pituitary gland. "Chemokines, such as CXCL8 (or interleukin (IL)-8), CCL2, CCL3, and CCL4, are secreted by pituitary tumors and non-tumor cells, such as macrophages, lymphocytes, or fibroblasts, and modulate the microenvironment composition." (PMID 37958702, 2023).
Pneumovirus Infections (1 paper, 2009). Infections with viruses of the genus PNEUMOVIRUS, family PARAMYXOVIRIDAE. "Our data suggest that that IFNγ and CCL3 signaling pathways, both crucial features of the response to pneumovirus infection, interact in a hierarchical fashion, as IFNγ does not elicit neutrophil recruitment on its own, but is crucial for CCL3 to function effectively." (PMID 19298652, 2009).
polyp (1 paper, 2024). A usually exophytic mass attached to the underlying tissue by a broad base or a thin stalk. "For CCL3, the histological type significantly affected its expression in polyp tissue, being higher in H and T than in T-V and V lesions, but not in normal mucosa." (PMID 38338661, 2024).
postmenopausal osteoporosis (1 paper, 2023). Metabolic disorder associated with fractures of the femoral neck, vertebrae, and distal forearm. "Patients with postmenopausal osteoporosis showed a significant increase in serum CCL3 compared with other groups, indicating that CCL3 may be a potential biomarker to predict disease severity of postmenopausal osteoporosis." (PMID 37475866, 2023).
primary hypertension (1 paper, 2023). "In other studies, in children with primary hypertension, the serum levels of CCL3 were not different than in normotensive children." (PMID 36769452, 2023).